ZNF528 (zinc finger protein 528)
Description:
May be involved in transcriptional regulation.
Synonyms: KIAA1827
Tractability: PROTAC: ubiquitination databases record sites on it.
Gene: Protein-coding gene on chromosome 19 (52,397,849 to 52,418,412, forward strand). Ensembl gene ENSG00000167555.
Subcellular location: Nucleus
Subcellular location (Human Protein Atlas): Nuclear speckles; Cytosol
Pathways (Reactome):
Gene expression (Transcription): Generic Transcription Pathway
Gene Ontology:
Molecular function: DNA-binding transcription factor activity, RNA polymerase II-specific; RNA polymerase II cis-regulatory region sequence-specific DNA binding
Biological process: regulation of transcription by RNA polymerase II; negative regulation of transcription by RNA polymerase II; regulation of DNA-templated transcription
Cellular component: nucleus; cytoplasm
Genetic constraint (gnomAD): Loss-of-function variants: 9 observed, 14.37 expected, observed/expected ratio (o/e) 0.63, 90% interval 0.38 to 1.09. The upper end of that interval is the gene's LOEUF score, 1.09, which puts it in group 4 of 6, group 1 being the genes least tolerant of losing a copy. Missense variants: 858 observed, 780.3 expected, observed/expected ratio (o/e) 1.1, 90% interval 1.04 to 1.16. Synonymous variants: 264 observed, 266.49 expected, observed/expected ratio (o/e) 0.99, 90% interval 0.89 to 1.1.
Homologues: Orthologues: chimpanzee ZNF528 (99% identical), macaque ZNF528 (94% identical). Paralogues in human: ZNF880 (64% identical), ZNF841 (52% identical), ZNF836 (50% identical), ZNF546 (47% identical), ZNF534 (46% identical), ZNF616 (46% identical), ZNF28 (45% identical), ZNF267 (45% identical), ZNF30 (45% identical), ZNF658 (44% identical), ZNF83 (44% identical), ZNF33B (44% identical), and 164 more.
Diseases named in the same sentence as ZNF528 in open-access papers:
ZNF528 is named in the same sentence as 10 diseases in open-access papers, as found by Europe PMC text mining. Sharing a sentence is not in itself a finding about the gene and the disease. The quoted sentences say what the papers report.
glioblastoma (1 paper, 2022). The most malignant astrocytic tumor (WHO grade IV). "For the remaining seven DEPCGs (ZWILCH, RPGR, ZNF460, ZNF528, QTRT2, C5orf15 and CNTRL), no previous functional associations were found with glioblastoma progression, despite a number of them being associated with other cancer types." (PMID 36497269, 2022).
osteoporosis (1 paper, 2020). A condition of reduced bone mass, with decreased cortical thickness and a decrease in the number and size of the trabeculae of cancellous bone (but normal chemical composition), resulting in increased fracture incidence. "Further research is necessary to fully understand the role of ZNF528 and the observed variant in primary osteoporosis." (PMID 32722848, 2020). "Thus, the variant may enhance the binding of ZNF528 in bone‐related target genes supporting the role of this variant in osteoporosis pathogenesis." (PMID 32722848, 2020). "Altogether, the pathway and osteoporosis‐related gene enrichment patterns on ZNF528‐c.1282C > T are dramatically different from the ZNF528‐WT targeted pathways, further supporting our findings of their differences in global genomic binding profiles." (PMID 32722848, 2020). "Compared with the wild type, ZNF528‐c.1282C > T showed a global shift in genomic binding profile and pathway enrichment, possibly contributing to the pathophysiology of primary osteoporosis." (PMID 32722848, 2020). "More osteoporosis‐related genes were affected by ZNF528‐c.1282C > T compared with ZNF528‐WT." (PMID 32722848, 2020). "Notably, the results showed that the fraction of osteoporosis‐related genes in the ZNF528‐c.1282C > T unique target gene set is significantly higher than that of ZNF528‐WT unique gene set." (PMID 32722848, 2020). "We next examined whether ZNF528 target genes are likely to be osteoporosis‐related genes by comparing the unique target genes and the OsteoporosAtlas database." (PMID 32722848, 2020). "ZNF528 is a novel candidate gene for bone disorders and may function as a transcriptional regulator in pathways affecting bone morphology and contribute to the phenotype of primary osteoporosis in this family together with the COL1A2 deletion." (PMID 32722848, 2020).
cancer (2 papers, 2020 to 2022). A tumor composed of atypical neoplastic, often pleomorphic cells that invade other tissues. "RNA sequencing showed that wild‐type ZNF528 directly regulated 367 genes, many of which belong to cell cycle‐ and cancer‐related pathways." (PMID 32722848, 2020).
cardiovascular disease (1 paper, 2024). "No research has proven the role of the TF ZNF528 in regulating cardiovascular disease, but we verified its pathogenicity from heterogeneity module in this study." (PMID 38528561, 2024).
tumor (1 paper, 2025). "Of 22 differentially methylated promoters common between all LS tumor groups, seven inversely correlated with expression: ADHFE1, DAPP1, FBLIM1, GRIA4, HOXA3, KLF17, and ZNF528." (PMID 40753397, 2025).
ZNF528 also shares sentences with these, for which no sentence is quoted: adenoma (1 paper); bone disorder (1); juvenile osteoporosis (1); Osteopenia (1); sarcoma (1).